RETREG2 (reticulophagy regulator family member 2)
Description:
Endoplasmic reticulum (ER)-anchored autophagy regulator which exists in an inactive state under basal conditions but is activated following cellular stress. When activated, induces ER fragmentation and mediates ER delivery into lysosomes through sequestration into autophagosomes via interaction with ATG8 family proteins. Required for collagen quality control in a LIR motif-independent manner (By similarity).
Synonyms: C2orf17; FAM134A; MGC3035; MAG-2
Tractability: Antibody: UniProt predicts a signal peptide or a membrane-spanning region.
Gene: Protein-coding gene on chromosome 2 (219,176,225 to 219,185,475, forward strand). Ensembl gene ENSG00000144567.
Subcellular location: Endoplasmic reticulum membrane
Subcellular location (Human Protein Atlas): Cytosol; Golgi apparatus
Gene Ontology:
Molecular function: protein binding; endoplasmic reticulum-autophagosome adaptor activity
Biological process: substrate localization to autophagosome
Cellular component: endoplasmic reticulum membrane; membrane; endoplasmic reticulum
Genetic constraint (gnomAD): Loss-of-function variants: 20 observed, 47.46 expected, observed/expected ratio (o/e) 0.42, 90% interval 0.3 to 0.61. The upper end of that interval is the gene's LOEUF score, 0.61, which puts it in group 2 of 6, group 1 being the genes least tolerant of losing a copy. Missense variants: 593 observed, 603.68 expected, observed/expected ratio (o/e) 0.98, 90% interval 0.92 to 1.05. Synonymous variants: 299 observed, 266.45 expected, observed/expected ratio (o/e) 1.12, 90% interval 1.02 to 1.24.
Homologues: Orthologues: chimpanzee RETREG2 (99% identical), dog RETREG2 (93% identical), pig RETREG2 (91% identical), guinea pig RETREG2 (90% identical), rat Retreg2 (88% identical), mouse Retreg2 (86% identical), rabbit RETREG2 (85% identical).
Diseases named in the same sentence as RETREG2 in open-access papers:
RETREG2 is named in the same sentence as 15 diseases in open-access papers, as found by Europe PMC text mining. Sharing a sentence is not in itself a finding about the gene and the disease. The quoted sentences say what the papers report.
glioma (1 paper, 2021). A benign or malignant brain and spinal cord tumor that arises from glial cells (astrocytes, oligodendrocytes, ependymal cells). "Our study has revealed causal evidence for three novel genes (RETREG2, FAM178B and MVB12B) associated with glioma risk." (PMID 33504897, 2021). "RETREG2 (or FAM134A), FAM178B and MVB12B appear to be novel findings related to glioma risk." (PMID 33504897, 2021). "The MR and colocalisation results suggested that genetically predicted increased gene expression of 12 genes were associated with glioma, GBM and/or non-GBM risk, three of which are novel glioma susceptibility genes (RETREG2/FAM134A, FAM178B and MVB12B/FAM125B)." (PMID 33504897, 2021).
cancer (3 papers, 2021 to 2023). A tumor composed of atypical neoplastic, often pleomorphic cells that invade other tissues. "Similarly, cancer-secreted EVPs containing miR-940 are internalized by osteoblasts, targeting Rho GTPase activating protein 1 (ARHGAP1) and reticulophagy regulator family member 2 (FAM134A)." (PMID 38707985, 2023).
RETREG2 also shares sentences with these, for which no sentence is quoted: cyst (5 papers); infection (3); lung carcinoma (2); acute myeloid leukemia (1); Cognitive impairment (1); oral cancer (1); oral candidiasis (1); oral squamous cell carcinoma (1); Parkinson disease (1); schizophrenia (1); toxoplasmosis (1); tumor (1); vascular dementia (1).